INS (insulin)
Diseases named in the same sentence as INS in open-access papers (continued):
Sharing a sentence is not in itself a finding about the gene and the disease.
gestational diabetes (continued). "A Poland study stated that 36.9% of the population knew diet and insulin use could help manage gestational diabetes." (PMID 38420077, 2024). "Our meta-analysis provides further evidence that metformin is a safe oral antihyperglycemic drug and has some benefits over insulin when used for the treatment of gestational diabetes, without an increased risk of short-term neonatal adverse outcomes." (PMID 36593391, 2023). "In addition, CXCL1 levels are also elevated in patients with T2DM and gestational diabetes mellitus, leading to decreased insulin secretion and degraded islet function." (PMID 36675322, 2023). "Predictors of insulin-requiring gestational diabetes mellitus and A2 gestational diabetes mellitus." (PMID 37680834, 2023). "During pregnancy, maternal insulin production rises and exogenous administration may be needed to maintain normal maternal serum concentrations and prevent the consequences of gestational diabetes." (PMID 37176607, 2023). "In this context, insulin, in addition to being one of the most prevalent hormones in breast milk, is also involved in a metabolic disease that affects many pregnant women, i.e., gestational diabetes mellitus (GDM)." (PMID 37191543, 2023). "Extracellular vesicles (EVs) are critical mediators of cell communication, playing important roles in regulating molecular cross-talk between different metabolic tissues and influencing insulin sensitivity in both healthy and gestational diabetes mellitus (GDM) pregnancies." (PMID 37650554, 2023). "Metformin and glibenclamide drugs may be effective and secure alternatives to insulin for the management of gestational diabetes, with metformin being preferred." (PMID 38021940, 2023). "For interventions for gestational diabetes, the pooled result of a meta-analysis of four randomized controlled trials suggests that diet counseling or insulin treatment (if needed) for women with the disorder is associated with a lower risk of macrosomia than usual care (OR 0.38; 95% CI 0.30–0.49)." (PMID 36750950, 2023). "As is known, the second and third trimesters are diabetogenic periods due to physiological insulin resistance, which could indicate that the body exceeds the buffering limit and is overstimulated, thereby leading to gestational diabetes." (PMID 37762934, 2023). "The results of a follow-up of a randomized study comparing metformin and insulin in gestational diabetes revealed that 97 children at the age of 18 months had similar neurodevelopmental performances in both motor and language domains regardless of exposure to either insulin or metformin." (PMID 37469977, 2023). "Given that gestational diabetes is generally believed to result from reductions in both insulin sensitivity and secretion, and that GLP-1 concentrations were associated with both of these, an association with gestational diabetes may have been expected." (PMID 37439859, 2023). "These alterations could be recovered with insulin, confirming the potential role of the insulin/adenosine/placental endothelial dysfunction in pregnancies complicated with gestational diabetes mellitus." (PMID 37507894, 2023). "Gestational diabetes mellitus (GDM) is an important metabolic disease with increased insulin counter-regulatory hormones generating glucose intolerance, an inflammatory environment, abnormalities in oxidative stress, and altering the profile of released cytokines and other hormones." (PMID 38138954, 2023). "We aimed to develop a score to predict future insulin dependency in gestational diabetes (GDM)." (PMID 38002781, 2023). "Similarly, in women with gestational diabetes mellitus (GDM) or pre-GDM, group-based prenatal care has been associated with significantly lower rates of progression from pre-GDM to GDM, lower rates of insulin prescription; and found to be more cost-effective than individual prenatal care." (PMID 37237255, 2023). "Another serological marker related to gestational diabetes is insulin." (PMID 37374343, 2023).
gestational diabetes (continued). "However, when the body cannot compensate for this resistance by producing enough insulin, gestational diabetes can develop." (PMID 37374343, 2023). "Consequently, the only basis for comparison lies with singleton pregnancies that necessitated insulin treatment in the context of gestational diabetes mellitus." (PMID 37959321, 2023). "However, when maternal pancreatic function cannot overcome this insulin resistance, aberrant glucose control ensues and results in elevated maternal blood glucose levels and a diagnosis of gestational diabetes mellitus (GDM)." (PMID 37671402, 2023). "Fifty-nine women had gestational diabetes mellitus already treated with a median dose of 32 insulin units per day (group 1), 53 had gestational diabetes mellitus on medical nutrition therapy (group 2), and 40 women were without gestational diabetes mellitus (group 3)." (PMID 35052298, 2022). "The most conclusive evidence comes from the metformin versus insulin for the treatment of gestational diabetes (MiG) trial where 752 women were randomised to metformin or insulin when MNT failed, which reported no increased risk of perinatal morbidity with metformin, compared to insulin." (PMID 36131291, 2022). "Women with pre-gestational diabetes involves both T1D and T2D and may differ in their ability to produce insulin." (PMID 35329371, 2022). "Although arsenic exposure during pregnancy has been consistently associated with gestational diabetes mellitus, we found no clear evidence for an adverse effect on postpartum insulin resistance or beta cell function." (PMID 35031057, 2022). "Previous studies have reported that insulin treatment might be an independent predictor of DOLII among women with gestational diabetes." (PMID 36451171, 2022). "Gestational diabetes affects pregnant women when the pancreas are unable to produce enough insulin." (PMID 36249249, 2022). "Our work raises the hypothesis that αMD can favorably modulate insulin sensitivity in the third trimester of pregnancy in previously insulin-treated women with gestational diabetes who receive glucocorticoids." (PMID 35052298, 2022). "The mother developed gestational diabetes during pregnancy and was treated with insulin." (PMID 35970867, 2022). "In pregnancies complicated by maternal obesity and gestational diabetes mellitus, there is strong evidence to suggest that the insulin signaling pathway in the placenta may be impaired." (PMID 35327377, 2022). "Our work raises the hypothesis that αMD can favorably modulate insulin sensitivity in the third trimester of pregnancy in previously insulin-treated gestational diabetes women undergoing GCs treatment, at variance with previous evidence." (PMID 35052298, 2022). "For instance, maternal obesity and excessive gestational weight gain (GWG) contribute to increased maternal insulin secretion, elevated risk of developing gestational diabetes mellitus (GDM), and possibly increased cord blood insulin and C-peptide concentration." (PMID 36224521, 2022). "Unlike type 1 diabetes, gestational diabetes is not caused by a shortage of insulin, but by a variety of different hormones released during pregnancy." (PMID 35867537, 2022). "This study may be the first to demonstrate that a higher protein and lower carbohydrate meal in women with gestational diabetes can result in lower glucose and insulin AUC and lower postprandial blood glucose values, consistent with our hypothesis." (PMID 36147835, 2022). "However, in some cases an abnormally increased insulin resistance and/or dysfunction in insulin secretion are seen, introducing a hyperglycemic state termed gestational diabetes mellitus (GDM)." (PMID 35025980, 2022). "In addition, recent reports demonstrated that melatonin receptor 1B (MTNR1B) gene polymorphisms may influence insulin secretion and pancreatic glucose sensing, causing gestational diabetes mellitus (GDM)." (PMID 36552008, 2022).
gestational diabetes (continued). "Gestational diabetes can occur during pregnancy when the natural production of diabetogenic hormones from the placenta, which induces insulin resistance, cannot be compensated sufficiently by increased insulin production from the mother." (PMID 35455074, 2022). "Here, we review calcium dynamics in islets in response to pregnancy-induced changes in hormones and signaling molecules, and how these changes may enhance insulin secretion to stave off gestational diabetes." (PMID 35399944, 2022). "It is worth noting that it is unclear whether the elevated plasma SP-D levels are directly related to gestational diabetes or whether the elevated plasma SP-D levels are due to insulin resistance or inflammatory status in gestational diabetes." (PMID 35317741, 2022). "The application of oral hypoglycemic drug metformin in blood glucose control of gestational diabetes can play a hypoglycemic effect equivalent to insulin and can control the weight of pregnant women, reduce the rate of abortion and cesarean section, and improve pregnancy outcomes." (PMID 35910483, 2022). "However, if pancreatic beta-cells are incapable of producing sufficient insulin, gestational diabetes mellitus (GDM), one of the most common complications of pregnancy, will develop." (PMID 36360995, 2022). "Two systematic reviews and meta-analyses of RCTs on metformin vs placebo/insulin in PCOS pregnancies or in gestational diabetes mellitus supports a higher weight among metformin exposed children, which in turn might impact the timing of puberty." (PMID 34499672, 2021). "The identification of pregnant women with Gestational Diabetes Mellitus (GDM) who will require insulin therapy, may modify their management to closer monitoring and probable early interventions." (PMID 34601490, 2021). "Thus, in the majority of reported cases, insulin therapy was instituted on the basis of maternal capillary blood glucose upon diet, as recommended in “common” gestational diabetes, or on the discovery of macrosomia by routine US." (PMID 35069449, 2021). "The mother had gestational diabetes requiring insulin therapy." (PMID 33927848, 2021). "Migrant women were also more likely than Australian born women to be birthing their first baby (45.3% vs 43% respectively); develop more gestational diabetes managed with diet (9.5% vs 4.0%) and insulin (6.1% vs 2.8%); and experience more suspected fetal growth restriction (5.8% vs 4.3%)." (PMID 34051749, 2021). "Other diagnoses included gestational diabetes requiring insulin, acute appendicitis during the first trimester which was managed conservatively, ascites associated with severe pre-eclampsia, as well as hydatidiform mole and intrauterine fetal death of a co-twin." (PMID 33431902, 2021). "The diagnosis of gestational diabetes is usually very stressful for pregnant women, especially because they fear that insulin treatment may become necessary." (PMID 34640439, 2021). "Gestational diabetes mellitus (GDM) enhances fetal insulin secretion and fetal growth." (PMID 35145481, 2021). "Women born in Australia were at high risk of birthing a large for gestational age infant in the presence of insulin-requiring gestational diabetes mellitus, but this risk was not significant for those with the diet-controlled type." (PMID 34556066, 2021). "However, when β-cells of the pregnant woman are unable to produce an adequate amount of insulin to face this increased demand, the physiological reduction in insulin sensitivity becomes a pathological condition, i.e., the gestational diabetes mellitus (GDM)." (PMID 35011145, 2021). "A number of miRNAs have been demonstrated to serve crucial roles in gestational diabetes mellitus by protecting pancreatic β-cell function, affecting insulin resistance, insulin sensitivity as well as liver gluconeogenesis, for instance, miR-143, miR-351, and miR-96." (PMID 34007244, 2021).
gestational diabetes (continued). "“if a pregnant mother has gestational diabetes, that mother have to control the diet, do frequent blood investigations, and they need to admit to the hospital several times for checkups, sometimes they have to take medicines or insulin." (PMID 34758774, 2021). "However, breastfeeding at least among obese women with gestational diabetes can influence postpartum insulin concentration." (PMID 33673568, 2021). "Inositol, an insulin sensitizer, has been trialled for gestational diabetes prevention." (PMID 32433604, 2021). "Fifteen to 30% of women with Gestational Diabetes Mellitus (GDM) require insulin therapy." (PMID 34601490, 2021). "Twenty-one participants (75%) had gestational diabetes, treated with metformin or insulin." (PMID 34301285, 2021). "A larger randomized controlled trial that compared metformin with insulin in the treatment of gestational diabetes (MiG trial) suggested that metformin, alone or with supplemental insulin, is an effective and safe treatment option in regards to glycemic control and feto-maternal outcomes." (PMID 34589334, 2021). "Insulin remains the pharmacological treatment of choice in pregnant women with T2DM or gestational diabetes; however, these patients should be referred to speciality centres and require multiple daily injections of insulin, and thus are not within scope for this study." (PMID 33098260, 2021). "Whether exposure to DE-71 in dams produced gestational diabetes followed by a normalization in insulin sensitivity after pregnancy when dams were tested is unclear." (PMID 33093533, 2020). "A possible link of the need for insulin administration with the presence of thyroid disease (in the context of increased risk for gestational diabetes with coexisting hypothyroidism) was also not observed." (PMID 32079162, 2020). "There was a history of gestational diabetes in the mother requiring insulin treatment." (PMID 31989990, 2020). "Furthermore, high levels of miR-16, which are seen in T1D patients, are also found in women diagnosed with gestational diabetes mellitus and are involved in insulin sensitivity." (PMID 32502186, 2020). "Neonatal hypoglycemia is one of the important concerns with insulin in gestational diabetes." (PMID 33403188, 2020). "The insulin resistant state of pregnancy may be particularly sensitive to climate factors, which could impact the body’s metabolism, increasing gestational diabetes (GDM) risk." (PMID 33168031, 2020). "The Fit for Delivery intervention in low risk women showed a reduction in insulin and leptin concentrations, but this did not reduce the incidence of gestational diabetes, the primary outcome." (PMID 31601214, 2019). "This could reduce the capacity of the beta-cells to secrete adequate levels of insulin to compensate for the insulin resistance induced by the progression of pregnancy and therefore lead to the development of gestational diabetes." (PMID 30987614, 2019). "Additionally, should a smoker develop certain complications (most commonly, diagnosis of gestational diabetes requiring metformin or insulin treatment), she will require transfer out to another specialist antenatal clinic, leading to drop out." (PMID 31481110, 2019). "In this cohort, as expected for gestational diabetes, exposure to ADDs increased over the course of pregnancy with most use occurring in the 3rd trimester when the diagnosis is made (reflected by the use of sulfonylureas and insulin)." (PMID 31775682, 2019). "It is known that vitamin D deficiency may be a factor participating in the development of gestational diabetes mellitus, as vitamin D regulates insulin production and insulin response in tissues." (PMID 31083424, 2019). "When analyzed only in neonates born to mothers without gestational diabetes (n = 848), the median cord blood insulin level was unchanged (18.75–50.7), while for neonates born to mothers with gestational diabetes (n = 34) the median value was 37.11 pmol/L (25.29– 65.63)." (PMID 31031804, 2019).
gestational diabetes (continued). "However, the exercise intervention lead to a reduction in gestational diabetes mellitus and systolic blood pressure in late pregnancy, as well as reduced circulating insulin levels tree moths postpartum." (PMID 29856768, 2018). "Standard drug for patients with gestational diabetes who require medication, insulin is available." (PMID 30820209, 2018). "She developed gestational diabetes mellitus requiring insulin treatment." (PMID 28588004, 2017). "There is little information available on the effect of Gestational diabetes mellitus (GDM) treatment (diet or insulin) on placental lipid carriers, which may influence fetal fat accretion." (PMID 28587267, 2017). "Summary of outcomes comparing glyburide with insulin in women with gestational diabetes." (PMID 28771572, 2017). "In Japanese women with recent gestational diabetes, ≥6 months of high-intensity breastfeeding significantly inhibited the development of abnormal glucose tolerance during the first year (up to 14 months) postpartum, possibly by improving insulin sensitivity." (PMID 28725256, 2017). "Other studies have shown that infants born to mothers with gestational diabetes may be more vulnerable to the effects of low circulating DHA through altered fetal insulin sensitivity." (PMID 28574453, 2017). "Furthermore, Chinese medicines in combination with insulin exhibited better clinical effect in the treatment of gestational diabetes." (PMID 27030797, 2016). "Foetal insulin levels were also higher in the pre-gestational diabetes group." (PMID 27736899, 2016). "In the gestational diabetes subjects insulin doses ranged from 4 to 52 units daily." (PMID 27736899, 2016). "The fact that insulin is higher in gestational diabetes mellitus offspring may suggest dysregulation of insulin signaling at birth which is compatible with an adaptation for elevated maternal glucose levels." (PMID 27440187, 2016). "To further test this hypothesis we studied fetal brain development in pregnancies of insulin-sensitive mothers, insulin-resistant mothers and mothers with gestational diabetes." (PMID 27344314, 2016). "Additionally, in the Metformin in Gestational diabetes (MiG) study, children of women randomised to the metformin group had lower visceral body fat at 2 years than did children of women randomised to insulin, despite similarities in birthweight." (PMID 26165398, 2015). "Compared with gestational diabetes mellitus rats as the control group, Zuogui Wan can change the indexes of fasting blood glucose, body weight, total cholesterol, insulin, and metabolism cage index significantly in Zuogui Wan gestational diabetes mellitus group." (PMID 25136475, 2014). "Some random control trials have demonstrated that for gestational diabetes, a comprehensive management of dietary and necessary insulin could significantly improve the perinatal outcomes." (PMID 24438028, 2014). "Third, saturated fat and cholesterol, which are components of red and processed meats (part of fast food in our study), have shown to adversely affect not only insulin sensitivity but also beta cell function, relevant in the pathophysiology of gestational diabetes." (PMID 25215961, 2014). "Therefore, it is clear that Zuogui Wan can reduce the level of total cholesterol and insulin when given in embryonic rats of gestational diabetes mellitus." (PMID 25136475, 2014). "She developed gestational diabetes, treated with diet and insulin." (PMID 23849162, 2013). "This is the first study reporting on the metabolic risk profile of overweight and obese women in early lactation, although early postpartum fasting plasma glucose and insulin levels have been reported among obese women with recent gestational diabetes mellitus." (PMID 23667649, 2013).